BRAF (B-Raf proto-oncogene, serine/threonine kinase)
Diseases named in the same sentence as BRAF in open-access papers (continued):
Sharing a sentence is not in itself a finding about the gene and the disease.
thyroid cancer (continued). "In human thyroid cancers, a high frequency of 22q loss was preferentially associated with RAS-mutated PTC and poorly differentiated thyroid carcinomas as compared to BRAF-mutated tumors." (PMID 34065786, 2021). "Aggressive variants of PTC had a higher prevalence of the BRAF mutation and a lower prevalence of RAS mutation than other types of thyroid cancer." (PMID 33672707, 2021). "Several BRAF inhibitors (BRAFi) for thyroid cancer have been approved by food and drug administration in America, such as vemurafenib, dabrafenib, etc8." (PMID 33613767, 2021). "The mechanisms of BRAF inhibitors response are still poorly understood in a thyroid cancer (TC) context." (PMID 34072194, 2021). "In fact, well-differentiated thyroid carcinomas mostly display gene expression features consistent with two major signatures, BRAF- and RAS-like." (PMID 33543394, 2021). "BRAF and RAS mutations remain the principal genes involved in aggressive thyroid carcinomas, occurring in 33% and 45% of the PDTCs, respectively." (PMID 34830540, 2021). "Four thyroid carcinomas with wildtype BRAF were classified as malignant nodules by NGS, and five BRAF V600E mutations were detected by ARMS-qPCR and missed by NGS." (PMID 34322384, 2021). "PTEN and BRAF (V600E) are confirmed mutant genes in thyroid carcinoma, and they are closely related to the clinical manifestations of thyroid carcinoma malignancy." (PMID 34930256, 2021). "Consistently, our findings revealed that in a thyroid carcinoma cell model with BRAF V600E genetic background, the upregulation of RAC1 activity is able to potentiate the positive impact on NIS expression induced by MEK inhibition." (PMID 34831012, 2021). "Multiple studies have shown that BRAF p.V600E correlates with aggressive features of thyroid carcinoma such as extrathyroidal extensions, vascular invasion, larger nodule size, advanced staging, lymph node metastasis and recurrence." (PMID 33052631, 2021). "By contrast, thyroid cancer cells with wild‐type BRAF were less sensitive to dabrafenib treatment, and their viability was significantly inhibited only at higher drug concentrations." (PMID 32935463, 2020). "Compared to early-stage WDTC, co-occurrence of BRAF and TERT mutations are common in locally advanced (T4) thyroid cancer and are associated with an increased risk of recurrence." (PMID 32415114, 2020). "Overall, we confirmed the co-occurrence of senescent thyroid cells and CAFs at the invasive front of BRAF-driven human thyroid cancers." (PMID 31906302, 2020). "Most thyroid cancers are closely related to MAPK, VEGF, and PI3K signaling pathways, while BRAF, RAS and RET genes have higher mutation rates, which provides molecular targets for thyroid cancer." (PMID 33519470, 2020). "A subset of BRAF + thyroid cancers will present with aggressive T4 tumors and or recur, but we do not know why." (PMID 32415114, 2020). "Of the 50 thyroid nodule cases, BRAF, NRAS, and TERT promoter mutation correctly detected thyroid cancer respectively in 12, 7, and 5 cases from 39 malignancy cases." (PMID 33247684, 2020). "We then examined the SHP2 dependency of feedback activation in BRAF mutant thyroid cancer cell line SW1736 used in the reported study." (PMID 32076487, 2020). "Evidence suggests that BRAF inhibitory agents restore RAI uptake in BRAFV600E iodine-refractory thyroid cancer cells, probably by reactivating the expression of thyroid-specific genes involved in iodine metabolism." (PMID 32748840, 2020). "Overall, advanced T4 thyroid cancers more frequently harbored TERT mutations and had a 10-fold higher rate of co-occurring BRAF and TERT mutations." (PMID 32415114, 2020).
thyroid cancer (continued). "To deeper investigate the role of the IDO1-Kynurenine-AhR pathway in thyroid cancer pathogenesis, we analyzed AhR expression in human-derived thyroid cancers and in thyroid tumors from BRAF-transgenic mice." (PMID 31936153, 2020). "Among the 293 mutation-positive specimens, 287 cases (97.9%) were identified as thyroid cancer, including 15 NIFTP, whereas six mutation-positive specimens were confirmed as follicular adenoma (four with RAS-positive and two with BRAF-positive)." (PMID 32781560, 2020). "In summary, the results of this study show that T4 well differentiated thyroid cancer develops primarily via BRAF V600E-initiated pathway, and more than half of them also carry TERT mutations." (PMID 32415114, 2020). "Both BRAF FOXE1+/+ and BRAF FOXE1+/− mice instead developed thyroid cancers, which show different morphologies." (PMID 33375029, 2020). "Six molecular targets of thyroid cancer including BRAF, RET, NTRK1, G-GAS, K-RAS, and N-RAS have already been reported." (PMID 33519470, 2020). "We identified NF2 mutations associated with resistance to the BRAF inhibitor dabrafenib in BRAF mutant thyroid carcinoma cell lines." (PMID 33205120, 2020). "This phenomenon explains why BRAF exon 15 p.V600E thyroid carcinomas are resistant to radioiodine treatment." (PMID 33260892, 2020). "The different BRAF statuses in coincident thyroid carcinoma foci within the same organ outline a special challenge for molecular follow-up and therapeutic decision-making." (PMID 31963551, 2020). "The current most prevalent targeted therapy approved by the FDA for thyroid cancer is the administration of the BRAF inhibitor dabrafenib combined with the MAPK inhibitor trametinib." (PMID 31443155, 2019). "In line with this, pharmacological targeting of CSF-1/CSF-1R inhibits TAMs and impairs BRAF-induced thyroid cancer progression in BRAF-V600E transgenic mice." (PMID 31113465, 2019). "The anti-cancer effect of BRAF inhibitors was also studied in a orthotopic mouse model of anaplastic thyroid carcinoma, which had been obtained by injecting a thyroid cancer cell line in mice with severe combined immunodeficiency." (PMID 31762942, 2019). "The results of the present study show that the selective BRAF-inhibitor, PLX4720, inhibits the basal and the TNFα-stimulated secretion of CXCL8 in BRAFV600E mutated thyroid cancer cell lines (BCPAP, 8305C and 8505C)." (PMID 30867499, 2019). "Thyroid cancers with BRAF and TERT tend to have more aggressive phenotypes and often become resistant to traditional therapies." (PMID 31810221, 2019). "The overexpression of NF-κB transcription factors is common in thyroid cancer, particularly in PDTC and ATC, and is associated with larger tumor size, nodal metastases, extrathyroidal extension, and BRAF p.V600E mutation." (PMID 31835496, 2019). "Thyroid cancer has these types of SNV-drivers present in BRAF in 55.8% of cases, the next qualifying genes being TTN, TTN-AS1, NRAS and KMT2C all with a low incidence rate of 1.3%." (PMID 31530827, 2019). "This review illustrates how different immune cells contribute to thyroid cancer development and the rationale for the antitumor effects of ICIs in combination with BRAF/TK inhibitors." (PMID 31412566, 2019). "Constitutive or enhanced signaling of this pathway is common in thyroid cancer, and elevated AKT activity has been associated with tumor size and invasion in both FTC and PTC, with the exception of tumors with BRAF activating mutations." (PMID 31312183, 2019). "In thyroid cancer, SLC1A5 is reported to be expressed in only tumor cells and related to the BRAF V600E mutation, which is associated with extrathyroidal extension, advanced TNM stage, lymph node metastasis, multifocality and recurrence." (PMID 31409775, 2019).
thyroid cancer (continued). "Aim of this study was to test the effect of the BRAF-inhibitor (PLX4720) on the basal and TNF-α-induced CXCL8 secretions in BRAFV600E mutated (BCPAP, 8305C, 8505C), in RET/PTC rearranged (TPC-1) thyroid-cancer-cell-lines and in normal-human-thyrocytes (NHT)." (PMID 30867499, 2019). "The BRAF V600E and TERT promoter mutations (C228T and C250T) have been extensively related to prognosis in thyroid cancer." (PMID 30884810, 2019). "BRAF also qualifies in the top five cancer genes in two instances: skin cutaneous melanoma and thyroid cancer." (PMID 31530827, 2019). "Combination strategies involving immune checkpoint inhibitors (ICIs) with tyrosine kinase (TK) or serine/threonine protein kinase B-raf (BRAF) inhibitors are showing considerable promise in the treatment of advanced thyroid cancer." (PMID 31412566, 2019). "The induction of RET/PTC1 and BRAF p.V600E in thyrocytes and thyroid cancer cells resulted in the activation of NF-kB." (PMID 31835496, 2019). "The TCGA database identified the following two major gene expression signatures in thyroid cancers (mostly PTC): BRAF P.V600E-like and RAS-like groups." (PMID 31835496, 2019). "Despite its important role in the pathogenesis of thyroid cancer, the BRAF/MEK/ERK signaling pathway is unlikely the key downstream target of anlotinib." (PMID 30139768, 2019). "Thyroid cancer was particularly remarkable with its low driver count and substantial influence of the gene BRAF as a driver." (PMID 31530827, 2019). "A genomic study performed in a large cohort of PTC from Saudi Arabia (n = 886), where thyroid cancer is the second most common cancer in women, showed a high prevalence of BRAF (59%), HRAS (2%), and NRAS (1%), similar to other cohorts." (PMID 31835496, 2019). "The BRAF mutation, confirmed as the most common driver mutational event involved in PTC, has been identified as a highly specific marker of thyroid cancer as the mutation occurs exclusively in thyroid malignancy rather than in benignancy." (PMID 30915113, 2019). "BRAF-mutant tumors (60–70% of thyroid cancers) are more likely to be resistant to radioiodide, partly due to decreased NIS expression, but also due to impaired PM targeting through mechanisms that remain ill-defined." (PMID 31310151, 2019). "BRAF-targeted paired box gene-8 (PAX8), a thyroid-specific transcription factor, generally dysregulated in BRAF-mutated thyroid cancer." (PMID 30760304, 2019). "Further, as shown in thyroid cancer cells harboring BRAFV600E mutation, the binding of the co-chaperone BAG3 to BRAF protected it from degradation by inhibiting HSP70-mediated delivery to the proteasome." (PMID 31841566, 2019). "To this aim, we tested the possibility of a cross-talk between the Shh pathway and the RAS/BRAF oncogenic signaling cascade active in most thyroid cancer cells." (PMID 29435119, 2018). "All these findings hence suggest that oncogenic RAS/BRAF/MEK pathway influences Shh pathway activation in thyroid cancer cells generating a ligand independent (cyclopamine-sensitive), non-canonical mechanism of activation." (PMID 29435119, 2018). "BRAF-transformed thyroid cancer cells respond to treatment with PLX4032, a selective inhibitor of BRAFV600E kinase, which inhibits MAPK-dependent cell proliferation." (PMID 29467389, 2018). "Our data corroborate the idea that PD-L1 and PD-L2 gene expression is a downstream target of BRAF signaling, as previously suggested for PD-L1 in thyroid carcinoma and demonstrated in myeloma." (PMID 30123257, 2018). "It was further demonstrated that combination with HER inhibitor lapatinib prevented MAPK rebound and sensitized BRAF-mutant thyroid cancer cells to BRAF or MEK inhibitors." (PMID 28423638, 2017).
thyroid cancer (continued). "Novel molecular-based management strategies, such as RET-PTC, RAS, BRAF (V600E), and TERT mutations for thyroid nodules and thyroid cancer are the most exciting developments in thyroid-cancer medicine." (PMID 29100371, 2017). "Previous studies demonstrated BRAFV600E-dependent inhibition in thyroid cancer cells by BRAF inhibitors." (PMID 28423638, 2017). "Consistent with some BRAF mouse models of thyroid cancer we observed a relatively long latency of tumor development." (PMID 28350298, 2017). "BRAF and RAS mutations activate the MAPK signaling pathway in thyroid cancer, inducing the expression of phosphorylated ERK1/2, JNK, and P38 kinase, amplifying oncogenicity." (PMID 27462868, 2017). "The interesting fact that BRAF inhibition in 8505C cells induces EMT from our study suggests that sustained BRAF inhibitor treatment in thyroid cancer would do more harm than good, which raises an important clinical issue." (PMID 27880942, 2017). "On the basis of our previous findings, this present study goes one step further and aims to investigate the effect of acquired resistance of BRAF inhibitor on EMT in BRAF mutant thyroid cancer cells." (PMID 27880942, 2017). "My colleagues at Memorial Sloan Kettering Cancer Center developed a mouse model for thyroid cancer in order to study the effect of the BRAF driver oncogene on a molecular basis and its role in creating the tumor phenotype." (PMID 28117292, 2017). "Stable transgenic expression of oncogenic BRAF (BRAFV600E) in thyroid epithelial cells has recently been shown to induce thyroid cancer in adult zebrafish." (PMID 29376139, 2017). "Knockdown of WIPF1 robustly inhibited anchorage-independent colony formation, migration, and invasion of thyroid cancer cells and suppressed xenograft thyroid cancer tumor growth and vascular invasion, mimicking the effects of BRAF knockdown." (PMID 27863429, 2017). "This is well consistent with the major role of BRAF V600E in the invasive and metastatic behavior of thyroid cancer." (PMID 27863429, 2017). "The present study goes one step further and aims to investigate the effect of acquired resistance of BRAF inhibitor on epithelial-to-mesenchymal transition (EMT) in BRAF mutant thyroid cancer cells and the effect of dual inhibition from combinatorial therapy." (PMID 27880942, 2017). "The discovery of novel molecular-based prognostic markers for thyroid cancer, such as RET-PTC, RAS, BRAF (V600E), PTEN and TERT mutations, are among the most notable developments in thyroid cancer-related medicine." (PMID 29254191, 2017). "Based on this study, point mutations were identified in 30-83% of specific thyroid cancer types, and among PTC, the genetic profiles of follicular variant PTC are dominated by RAS mutation while the BRAF is the major mutation in CPTC." (PMID 28423545, 2017). "In a mouse model of thyroid cancer genetic inactivation of TSH receptor attenuated tumor initiation suggesting that TSHR signaling cooperates with oncogenic BRAF." (PMID 28350298, 2017). "In thyroid cancer, dysfunction of COLL1 and LOX genes, promoted by BRAF and PTEN knockdown, were associated with ripping stiffen of Col1 matrix, enhancing cell motility and tumor progression." (PMID 28402931, 2017). "Recently, much work has been done on exploring mechanisms of resistance to BRAF inhibitors in various cancers including thyroid cancer." (PMID 28423638, 2017). "By contrast, evidences about sensitivity of thyroid carcinomas to BRAF inhibition are conflicting and it has been proposed that BRAF V600E thyroid carcinoma cells are less sensitive to BRAF inhibitors due to activation of parallel signaling pathways." (PMID 29033690, 2017). "We have reported the frequency of exon 15 BRAF mutations (48.5 %) in a pure sample of adult DTC patients from an ethnically different population with a high rate of consanguinity and high rate of thyroid cancer." (PMID 27387551, 2016).
thyroid cancer (continued). "This is in contrast to BRAF V600E mutation or TERT promoter mutations, which are associated with aggressiveness and poor clinical outcomes of thyroid cancer." (PMID 26817707, 2016). "Aim of this study was to test the effect of IFNγ on the basal and TNFα-stimulated secretion of CXCL8 in TCP-1 and BCPAP thyroid cancer cell lines (harboring RET/PTC rearrangement and BRAF V600e mutation, resp)." (PMID 27555670, 2016). "We propose that recruitment of multiple MAPKs affords colchicine, as shown here, broader activity across BRAF-mutant and BRAF-WT thyroid cancer cells." (PMID 26942566, 2016). "Our study demonstrated that Korean patients have a higher BRAF V600E prevalence and lower prevalence of the TERT promoter mutation and ALK rearrangement in thyroid cancers than do Western patients." (PMID 26857243, 2016). "We performed Sanger sequencing to detect BRAF V600E and TERT promoter mutations and both immunohistochemistry and fluorescence in situ hybridization to identify ALK rearrangement on 243 thyroid cancers." (PMID 26857243, 2016). "The molecular pathogenesis of thyroid cancer involves genetic alterations in both oncogenes and tumor suppressor genes, as exemplified by BRAF and RAS for the former and PTEN and RASAL1 for the latter." (PMID 26716505, 2016). "In thyroid cancer, BRAF V600E is the most common and the earliest genetic event in PTC, and it appears to be a good candidate gene for monitoring." (PMID 27871285, 2016). "BRAF (v-Raf murine sarcoma viral oncogene homolog B) mutation (V600E), which activates the MAPK pathway, is commonly observed in thyroid cancers." (PMID 26846696, 2016). "The KTC1 subpopulations described in this study provide a model of spontaneously acquired secondary resistance to BRAF V600E inhibitor in thyroid cancer cells." (PMID 27127178, 2016). "BRAF V600E and TERT promoter mutations can activate the mitogen-activated protein kinase (MAPK) signaling pathway in thyroid cancer." (PMID 26857243, 2016). "RET, BRAF and other protein kinases have been identified as major molecular players in thyroid cancer." (PMID 27058903, 2016). "For example, selumetinib (a MEK inhibitor) and vemurafenib and dabrafenib (mutant BRAF inhibitors) are clinically beneficial in thyroid cancer patients with advanced metastatic disease." (PMID 27384483, 2016). "This is the first study to investigate and compare genetic background (BRAF V600E, RET/PTC rearrangements, and RAS mutations) in differentiated thyroid carcinomas from iodine‐rich and iodine‐deficient countries." (PMID 27264674, 2016). "Meanwhile, various BRAF inhibitors are currently being tested in clinical trials on patients with refractory thyroid carcinoma, with varying results." (PMID 27410688, 2016). "Activation of this pathway in thyroid carcinomas is through RET/PTC rearrangement, RAS mutations and BRAF mutations." (PMID 27703585, 2016). "BRAF V600E mutation, RET rearrangements, and RAS mutations are the common genetic alterations in differentiated thyroid carcinomas derived from follicular thyroid cells." (PMID 27264674, 2016). "In this regard, we used the BRAF mRNA expression level as a surrogate marker for Braf function in thyroid carcinoma, although a substantial proportion of variation in the protein level cannot be explained wholly by changes in the mRNA level alone." (PMID 27410688, 2016). "Among the genetic alterations involved in thyroid tumorigenesis, BRAF mutations, RAS mutations, and RET rearrangements are important in differentiated thyroid carcinomas." (PMID 27264674, 2016). "As is well known, PTC, the most common thyroid carcinoma, frequently carries BRAF and RET/PTC, which have been identified as highly specific markers of thyroid cancer." (PMID 27654865, 2016). "Thyroid cancer (THCA) stood out for containing frequent and recurrent somatic mutations of BRAF p.V600E with 249 of 350 cases." (PMID 25600636, 2015).